TCF7L2 (transcription factor 7 like 2)
Diseases named in the same sentence as TCF7L2 in open-access papers (continued):
Sharing a sentence is not in itself a finding about the gene and the disease.
type 2 diabetes (continued). "First, we tested whether the T risk allele at the single nucleotide polymorphism (SNP) rs7903146 in the type 2 diabetes-associated locus TCF7L2 was associated with higher fasting glucose in our cohort, as previously shown by the MAGIC investigators." (PMID 25812009, 2015). "Accordingly, we tested the hypothesis that the efficacy response to linagliptin therapy, which acts via inhibition of incretin degradation, may be reduced in patients with type 2 diabetes who have high-risk TCF7L2 genotypes." (PMID 24906949, 2014). "In conclusion, the TCF7L2 rs7903146 (T) allele, the most unequivocal genetic factor influencing type 2 diabetes among Caucasians, is very common among Ghanaians and associated with type 2 diabetes and FPG." (PMID 24059590, 2013). "CYP2C9 encodes sulfonylurea metabolizing cytochrome P450 isoenzyme 2C9, ABCC8 and KCNJ11 genes encode proteins constituting ATP-sensitive K+ channel which is a therapeutic target for sulfonylureas, and TCF7L2 is a gene with the strongest association with type 2 diabetes." (PMID 24324494, 2013). "TCF7L2 is involved in insulin secretion, and the TCF7L2 rs7903146 single nucleotide polymorphism (SNP) constitutes the best established risk allele in Caucasian populations conferring an overall relative risk for type 2 diabetes of 1.44." (PMID 24059590, 2013). "In addition to the increased risk of type 2 diabetes, the TCF7L2 rs7903146 T allele has been associated with increased fasting glucose and HbA1c levels in genome-wide association studies (GWAS)." (PMID 22782288, 2012). "All of these expression traits could serve as causal explanations of how the TCF7L2 SNP leads to type 2 diabetes." (PMID 22584726, 2012). "Recent studies have shown that the genes which encode these two incretin hormones can be regulated by the effectors of the Wnt signaling pathway, including TCF7L2, a transcription factor identified recently by extensive genome wide association studies as an important type 2 diabetes risk gene." (PMID 22934027, 2012). "Common SNPs of TCF7L2 such as rs7903146 and rs12255372 are associated with type 2 diabetes." (PMID 23028378, 2012). "The type 2 diabetes C allele of TCF7L2 (rs7901695) was associated with a lower risk of islet autoimmunity compared to the TT genotype (HR: 0.66; 95% CI: 0.47–0.94; P = 0.022), but significance was lost after correcting for multiple comparisons (Pcorrected = 0.264)." (PMID 22558147, 2012). "In this study we hypothesised that different dietary intakes, in particular the relative intake levels of carbohydrates, fats, proteins or fibres, could modify the risk associated with the TCF7L2 rs7903146 T allele in incident type 2 diabetes." (PMID 22782288, 2012). "In addition to being linked to neoplastic transformation, variants in TCF7L2 are thought to be the most critical risk factors for type 2 diabetes." (PMID 22951069, 2012). "However, the risk of type 2 diabetes with the TCF7L2 T allele increased from 24% to 56% from the lowest (mean intake: 5.8 ± 0.8 g/4,184 kJ) to the highest (mean intake: 13.1 ± 2.2 g/4,184 kJ) quintile of fibre intake (pinteraction = 0.049)." (PMID 22782288, 2012). "It is interesting to note that, excluding the TCF7L2 SNP, three of the four variants most strongly associated with type 2 diabetes in the MAGIC study (MTNR1B rs10830963, PROX1 rs340874 and GCKR rs780094) have odds ratios of less than one in our South Asian populations." (PMID 21949744, 2011). "We replicated previous findings of associations for three SNPs in this Chinese population (rs10811661 in CDKN2A/B, rs10946398 in CDKAL1, and rs7903146 in TCF7L2) suggesting that some of the variants associated with type 2 diabetes in Europeans are also associated with the disease in Asians." (PMID 20161779, 2010). "However, we did identify a consistent association of this gene with type 2 diabetes in our Chinese population, further validating the contribution of TCF7L2 on susceptibility to the disease." (PMID 20161779, 2010).
type 2 diabetes (continued). "Transcription factor 7-like 2 (TCF7L2) has emerged as a consistently replicated susceptibility gene for type 2 diabetes, however, whether the TCF7L2 gene also has similar effects on the retinal microvasculature is less clear." (PMID 20478041, 2010). "Interestingly, two other TCF7L2 SNPs (rs11196218 and rs290487) were found to associate with type 2 diabetes in Chinese." (PMID 20161779, 2010). "How these SNPs located in introns affects the expression of TCF7L2, and therefore the risk of type 2 diabetes, remain largely unknown." (PMID 21286314, 2010). "Most of the genes associated with type 2 diabetes (TCF7L2, SLC30A8, HHEX, CDKAL1, CDKN2A/B and IGF2BP2) might be implicated in beta cell function." (PMID 20161779, 2010). "Keeping in mind that it is known as the hottest susceptibility gene for type 2 diabetes while being involved in glucose homeostasis, individual heterogeneity of TCF7L2 expression observed with M-CSF/macrophages in this study might be informative." (PMID 19341462, 2009). "Genetic variants in the gene encoding for TCF7L2 have been associated with type 2 diabetes and impaired cell function, but the mechanisms still remain unknown." (PMID 19924244, 2009). "The rs7903146 SNP in the TCF7L2 gene represents perhaps the most important gene polymorphism implicated in type 2 diabetes, since it is a relatively common variant that confers increased risk for diabetes and this association has been replicated across numerous independent samples." (PMID 18498660, 2008). "In this study, therefore, we investigated the association of common polymorphisms within the TCF7L2 gene with type 2 diabetes in a well-characterized UK-resident South Asian population of Punjabi ancestry, originating predominantly from the Mirpur area of Azad Kashmir, Pakistan." (PMID 18291022, 2008). "Interestingly, intronic SNP:s in the transcription factor 7-like 2 (TCF7L2) gene have been strongly associated with another complex phenotype, that of type 2 diabetes mellitus, in numerous populations of various ethnicities." (PMID 17487281, 2007). "Background/Objectives: The transcription factor 7-like 2 (TCF7L2) rs7903146 polymorphism has been strongly associated with type 2 diabetes mellitus (T2DM) in various populations; however, its impact on different ethnic groups is not fully understood." (PMID 40870963, 2025). "Indeed, TCF7L2 is considered to be the strongest risk factor for type 2 diabetes." (PMID 39060928, 2024). "The TCF7L2 gene (a major effector of the canonical Wnt/β-catenin pathway, and the most frequently mutated gene in some cancers, which has also been shown to be important for the degree of malignancy) is hitherto the strongest identified type 2 diabetes susceptibility gene." (PMID 37452207, 2023). "While genetic variants such as TBC1D4 and TCF7L2 result in up to 50% increased risk of type 2 diabetes by diminishing the incretin effect and impairing glucagon-like peptide 1–induced insulin secretion, a fiber-rich diet may stimulate glucagon-like peptide 1 and mitigate this genetic risk." (PMID 38049803, 2023). "Thus, TCF7L2 has been hypothesized as an important risk gene co-shared by type 2 diabetes, MetS, and psychiatric disorders, especially SCZ." (PMID 35874808, 2022). "The risk of type 2 diabetes mellitus (T2DM) increases by 50% in the presence of the risk allele of TCF7L2 gene at an individual level while the population attributable risk varies between 10-25% depending on the allele frequency." (PMID 36263318, 2022). "Background and aims: Several studies have shown that genetic polymorphisms of the transcription factor 7-like 2 (TCF7L2) are highly associated with the development of type 2 diabetes mellitus (T2DM) and its associated complications in several populations." (PMID 34073870, 2021).
type 2 diabetes (continued). "In adults, TCF7L2 has attracted widespread attention because of its significant genetic correlation with the high risk of type 2 diabetes (T2D), which alters the function and survival of pancreatic β cells." (PMID 34568447, 2021). "Some genetic association studies tried to investigate potential associations of Transcription Factor 7 Like 2 (TCF7L2) rs7903146 polymorphism with type 2 diabetes mellitus (T2DM)." (PMID 31312259, 2019). "Large scale association studies have found a significant association between type 2 diabetes mellitus (T2DM) and transcription factor 7-like 2 (TCF7L2) polymorphism rs7903146." (PMID 29514658, 2018). "The present study of 999 participants (499 SCZ patients and 500 healthy controls) was designed to investigate whether TCF7L2 SNPs previously associated with the risk of type 2 diabetes and SCZ in an Arab population are associated with the risk of SCZ in a Chinese Han population." (PMID 28404897, 2017). "Common non-coding variations within the TCF7L2 locus have a strong influence on type 2 diabetes (T2D) susceptibility through uncharacterised mechanisms." (PMID 22402060, 2013). "TCF7L2 is a confirmed type 2 diabetes (T2D) susceptibility gene and is now a major focus of T2D genetic and molecular research." (PMID 22247771, 2012). "Shortly after we presented this finding, TCF7L2 was identified as an important type 2 diabetes (T2D) risk gene in a large-scale genome-wide association study (GWAS)." (PMID 22934027, 2012). "In addition, the LAMA1 type 2 diabetes risk allele was associated with lower BMI within cases alone (P = 2×10−6 when testing BMI as a quantitative trait in cases) – a similar result was previously reported for the TCF7L2 risk allele." (PMID 22693455, 2012). "As TCF7L2 rs7903146 has been, in several studies, shown to associate more strongly with risk of type 2 diabetes among lean as compared with overweight individuals, we were concerned that some potential confounding could still be present after adjusting for BMI." (PMID 22782288, 2012). "Genome-wide association studies (GWAS) have repeatedly shown an association between non-coding variants in the TCF7L2 locus and risk for type 2 diabetes (T2D), implicating a role for cis-regulatory variation within this locus in disease etiology." (PMID 22590553, 2012). "As TCF7L2 rs7903146 has been associated with diminished incretin effect we investigated whether interaction between dietary intake of carbohydrate, fat, protein or fibre and this variant affects the risk of type 2 diabetes." (PMID 22782288, 2012). "Intronic variation located in a 92-kb interval within the Transcription Factor 7-Like 2 (TCF7L2) gene locus, a transcriptional regulator of canonical Wnt signaling, is the strongest determinant for type 2 diabetes (T2D) susceptibility identified to date." (PMID 22590553, 2012). "Extensive genome-wide association (GWA) studies revealed that TCF7L2 is a strong candidate for a type 2 diabetes gene, and several studies indicated that the presence of certain common single nucleotide polymorphisms (SNPs) in this gene might increase the incidence of this disease in human." (PMID 23028378, 2012). "It is well established that the rs7903146 variant in the transcription factor 7-like 2 gene (TCF7L2) is associated with type 2 diabetes (T2D)." (PMID 21814547, 2011). "Variants in the TCF7L2 have been shown to be associated with an increased risk for type 2 diabetes (T2D)." (PMID 21349175, 2011). "Single nucleotide polymorphisms (SNPs) rs7903146 and rs12255372 located within TCF7L2 gene have been identified as the strongest common genetic risk factors for development of type 2 diabetes (T2D)." (PMID 19789636, 2009). "Since it has been demonstrated that TCF7L2 variants also substantially influence normal birth-weight variations, a complex interplay between pathways that govern growth-related processes and susceptibility to type 2 diabetes could be hypothesized." (PMID 19936260, 2009).
type 2 diabetes (continued). "Common intronic single nucleotide polymorphisms (SNPs) within the transcription factor 7 - like 2 gene (TCF7L2) have been identified as genetic factors that significantly increase risk of type 2 diabetes (T2D)." (PMID 19789636, 2009). "We tested whether transcription factor 7 like-2 (TCF7L2) gene polymorphisms (rs12255372 and rs7903146), consistently associated with type 2 diabetes, are associated with plasma concentrations of inflammatory markers before and after three weeks of daily treatment with fenofibrate." (PMID 19825152, 2009). "Interactions between TCF7L2 genotype and diet have been reported on metabolic disease, such as type 2 diabetes and obesity." (PMID 40050721, 2025). "Transcription factor-7-like 2 (TCF7L2) is the most critical type 2 diabetes (T2D) gene identified to date." (PMID 40170676, 2025). "In recent decades, numerous studies have identified that the transcription factor 7-like 2 (TCF7L2) gene is one of the strongest genetic determinants associated with susceptibility to type 2 diabetes mellitus (T2DM), particularly through the well-characterized rs7903146 polymorphism 10-12." (PMID 40303486, 2025). "This study investigated the association of SNPs ADRB3(rs4994), ABCC8 (rs1799854),FTO (rs8050136) and TCF7L2(rs7901695 and rs12255372) with type 2diabetes in a sample of the Amazonian population." (PMID 39133695, 2024). "Type 2 diabetes, AD, and Parkinson’s disease are predicted to share similar dysregulated pathways involving TCF7L2 and CDKAL1." (PMID 38790243, 2024). "It has also been demonstrated that the genetic variation of TCF7L2 is highly correlated with obese traits in pigs and type-2 diabetes in humans." (PMID 38956836, 2024). "Polymorphisms of TCF7L2, IGF2BP2, CDKAL1, KCNQ1, and PPARG genes showed a strong contribution to type 2 diabetes." (PMID 36902173, 2023). "For example, it took a moderately large gene expression study in pancreatic islets to detect evidence that the gene TCF7L2 mediates the activity of the type 2 diabetes (T2D) loci with the same name." (PMID 37604891, 2023). "Tcf7l2 has also been proposed as a genetic factor that can explain the association between type 2 diabetes and non-alcoholic fatty liver disease (NAFLD), as genetic alterations in Tcf7l2 can make individuals susceptible to NAFLD." (PMID 36759348, 2023). "The pathway analysis showed that HNF1A and TCF7L2 genes were responsible for maturity-onset diabetes of the young (MODY) and human papillomavirus infection and prostate cancer pathways, respectively." (PMID 38096208, 2023). "Twenty-five of these were previously reported type 2 diabetes-associated variants, including those consistently identified in multiple populations (e.g. variants at KCNQ1 and TCF7L2) and others enriched in the Latino population (e.g. variants at SLC16A11)." (PMID 37148359, 2023). "This evidence suggests a probable pathway that links TNF-α and TCF7L2 in the co-existence of malaria and type 2 diabetes." (PMID 37215099, 2023). "In addition, the variant allele of the TCF7L2 SNP is an important genetic risk factor for type 2 diabetes mellitus and is also associated with increased cardiovascular abnormalities, suggesting that impaired postprandial lipid metabolism may be associated with higher cardiovascular risk." (PMID 38213786, 2023). "TCF7L2 rs7903146 and PNPLA3 rs738409 gene variants confer the strongest risk for type 2 diabetes mellitus (T2DM) and non-alcoholic fatty liver disease (NAFLD), respectively." (PMID 35897035, 2022). "Susceptibility genes for type 2 diabetes have been related to CFRD, specifically CAPN10 (calpain 10; OMIM * 605286) and TCF7L2 (transcription factor 7-like 2; OMIM * 602228)." (PMID 35887806, 2022). "Association of polymorphisms of genes TCF7L2, FABP2,KCNQ1, ADIPOQ with the prognosis of the development of type 2diabetes mellitus." (PMID 35434484, 2022).
type 2 diabetes (continued). "Among candidate genes related to type 2 diabetes (T2DM), one of the strongest genes is Transcription factor 7 like 2 (TCF7L2), regarding the Genome-Wide Association Studies." (PMID 36155628, 2022). "We used the ‘insulin secretion’ pPS of variants in eight genes associated with type 2 diabetes risk due to poor beta cell function: MTNR1B, HNF1A, GCK, TCF7L2, TMEM258, ADCY5, SLC3OA8 and ABO." (PMID 35247066, 2022). "TCF7L2 mRNA expression is reported to be the strongest type-2 diabetes candidate gene and inactivation of TCF7L2 leads to hepatic insulin resistance and decreased whole body glucose tolerance." (PMID 35958557, 2022). "In this trial, 300 participants with type 2 diabetes, aged 30–65 years with an identified TCF7L2 rs7903146 genotype, were studied." (PMID 35585604, 2022). "A genetic overlap between LADA and type 2 diabetes has also been observed; some studies have linked LADA to a risk locus on the transcription factor 7-like 2 (TCF7L2) gene, the strongest known genetic risk factor for type 2 diabetes (reviewed in 6)." (PMID 35846274, 2022). "The first GWAS repeated the previously known correlation between TCF7L2 and type 2 diabetes, which has been found in Icelandic populations." (PMID 34603195, 2021). "Previous studies have suggested that variation in Tcf7l2 expression alters glucose metabolism and induces a type 2 diabetes phenotype, and that high-fat feeding modulates Tcf7l2 expression in pancreatic islets, hepatocytes and adipocytes." (PMID 33068125, 2021). "In a small pharmacogenetic study, individuals with type 2 diabetes and the TCF7L2 rs7903146 CC genotype were matched with individuals with CT and TT genotypes and similar diabetes duration and BMI." (PMID 33594477, 2021). "In another, among 33 type 2 diabetes risk alleles, three (in FTO, TCF7L2 and PRC1) were found to be associated with breast cancer." (PMID 32705315, 2020). "Several locus-specific scores for type 2 diabetes, including JAZF1 and TCF7L2, are associated with C-peptide persistence." (PMID 31438962, 2019). "Variants in the transcription factor-7–like 2 (TCF7L2/TCF4) gene, involved in Wnt signaling, are associated with type 2 diabetes." (PMID 29967064, 2018). "Transcription factor 7-like 2 (TCF7L2, also known as TCF4) is demonstrated as a strong candidate for type 2 diabetes in recent extensive genome-wide association studies." (PMID 30733709, 2018). "The first association between the Wnt/β-catenin pathway and metabolic disease came about in 2004, in which some specific SNPs in β-catenin-independent WNT5B increased susceptibility for type 2 diabetes, initiating the discoveries of WNT10B and TCF7L2." (PMID 30065654, 2018). "The TCF7L2 rs7903146 variant is strongly associated with type 2 diabetes mellitus (T2DM)." (PMID 29736187, 2018). "TCF7L2 (transcription factor 7-like 2), an important component of WNT pathway, has been implicated in several human diseases including carcinogenesis, type 2 diabetes and bipolar disorder." (PMID 28499350, 2017). "It has also been reported recently that HDAC7 expression is increased in the pancreatic islets of type 2 diabetic patients and the expression of Tcf7l2 is promoted independently of histone acetylation to suppress insulin secretion." (PMID 28886131, 2017). "Similar patterns of association have been observed between maternal type 2 diabetes risk alleles and higher offspring birth weight at the GCK and TCF7L2 loci, both of which are known to influence fasting glucose levels in adults without diabetes." (PMID 28293907, 2017). "Genetic polymorphisms of the transcription factor 7-like 2 (TCF7L2) gene may be key agents in the etiology of type 2 diabetes mellitus (T2DM)." (PMID 29100364, 2017). "In line with our previous report, we observed an interaction between TCF7L2 rs7903146 and fiber intake on type 2 diabetes incidence." (PMID 27551309, 2016).